PLXNB2 (plexin B2)
Diseases named in the same sentence as PLXNB2 in open-access papers (continued):
Sharing a sentence is not in itself a finding about the gene and the disease.
psoriasis (8 papers, 2020 to 2024). An autoimmune condition characterized by red, well-delineated plaques with silvery scales that are usually on the extensor surfaces and scalp. "There was significant overexpression of plexin-B2 in dermal inflammatory cells of lesional skin of psoriasis patients when compared to controls skin." (PMID 38734848, 2024). "Hemida AS agreed with our study and found that was a significant positive correlation between plexin-B2 expression and psoriasis severity." (PMID 38734848, 2024). "In the present study we aimed to put a hint on the possible role of plexin B2 in psoriasis pathogenesis and correlate it with treatment by acetritine and NB-UVB." (PMID 38734848, 2024). "Reportedly, the axonal guide molecules, CD100 and Plexin-B2, are involved in the inflammatory process of psoriasis by activating NF-κB and NLRP3 inflammasome in keratinocytes." (PMID 32377228, 2020). "Plexin B2 could promote skin inflammation, as well as keratinocyte proliferation in psoriasis vulgaris; therefore, it may be used as a targeted therapy for psoriasis treatment." (PMID 38734848, 2024). "Also, a significantly higher tissue plexin-B2 level was observed in sever psoriasis (32.7 ± 3.8 pg/ml) in than moderate psoriasis (13.6 ± 2.1 pg/ml, p = 0.001)." (PMID 38734848, 2024). "Moreover, different immunohistochemical studies found a correlation between psoriasis severity and Smad7 and Plexin-B2 expression." (PMID 38003284, 2023). "PLXNB2 could regulate NF-κB-p65 and inflammasomes, thus aggravating inflammatory reaction in psoriasis." (PMID 35406030, 2022). "In addition to pro-wound healing functions in the skin and gut, CD100-plexin B2 interactions have been shown to be involved in psoriasis in both patients and mouse models." (PMID 35480230, 2022). "PLXNB2 is overexpressed in lesional skin in psoriasis and can promote skin inflammation." (PMID 34414666, 2021). "Activation of Plexin-B2 may play a role in the pathogenesis of psoriasis." (PMID 38734848, 2024). "PLXNB2 could promote inflammatory response both in allergic airway inflammation and psoriasis." (PMID 35406030, 2022). "The bound of soluble CD100 to PlxnB2 can upregulate NF-κB pathway, which induces NLRP3 inflammasome activation in keratinocytes of psoriasis patients." (PMID 34707607, 2021). "In summary, these findings indicate that CD100/PlxnB2, TTP, TNF, miR-155, and SAA might be potential therapeutic targets for psoriasis." (PMID 34707607, 2021).
breast carcinoma (7 papers, 2015 to 2025). "One of the future studies is to examine the association of PLXNB2 with CNS diseases and its contribution to regulating metastasis of breast cancer to the brain and other organs." (PMID 40818975, 2025). "We also analyzed a tissue microarray of advanced breast cancers collected at Northwestern University which showed a high expression of PLXNB2 across different breast cancer subtypes in association with distant metastasis." (PMID 40818975, 2025). "Loss of PLXNB2 (Plxnb2) reduces the formation of homotypic tumor cell clusters and heterotypic tumor-myeloid cell clusters, reducing spontaneous metastases in female mice bearing human (mouse) breast cancer." (PMID 40818975, 2025). "Considering our results and previous studies, PLXNB2 and ACOX3 are proposed as universal prognostic markers of breast cancer associated with chemotherapy resistance." (PMID 35335125, 2022). "Furthermore, the decreased level of PLXNB2 was correlated to unfavorable prognosis of breast cancer patients." (PMID 34367233, 2021). "In breast cancer and glioblastoma, Plexin-B2 is upregulated and promotes tumor growth and invasion." (PMID 34650052, 2021). "Thus, PLXNB2 is a therapeutic target for preventing new metastasis in breast cancer." (PMID 40818975, 2025). "Taken together, our data demonstrates that mouse Plxnb2 and human PLXNB2 play a similar role in promoting CTC-monocyte cluster formation and driving spontaneous metastases in breast cancer." (PMID 40818975, 2025). "To gain a better understanding of the downstream molecules and pathways in PLXNB2-mediated tumor cell clustering, we performed an MS-based global proteomics analysis of MDA-MB-231 breast cancer cells in suspension before and after clustering." (PMID 40818975, 2025). "After identifying PLXNB2’s role in promoting CTC clusters and metastasis, we continued to determine its function in tumor cell clustering in specific breast cancer subtypes such as TNBC and HER2+ in which metastasis is common." (PMID 40818975, 2025). "Here the authors find that the transmembrane protein Plexin-B2 (PLXNB2) mediates homotypic and heterotypic CTC cluster formation, driving lung metastasis in breast cancer mouse models." (PMID 40818975, 2025). "Plexin-B2 is up-regulated in primary tumors and enhances the formation of both homotypic tumor cell clusters and heterotypic CTC-myeloid cell clusters in metastasis of breast cancer, especially TNBC." (PMID 40818975, 2025). "Future therapeutics aimed at blocking PLXNB2 and SEMA4C/4A interactions can potentially serve as targeting strategies in breast cancer, especially TNBC and complement existing treatments, such as pembrolizumab, Sacituzumab72,73, and Palbociclib74 for improved outcomes." (PMID 40818975, 2025). "The newly identified role of PLXNB2 in CTC clustering in conjunction with its ligands SEMA4C in tumor cells and SEMA4A in monocytes promotes metastasis, and is correlated with lower OS and DMFS in the context of advanced breast cancer, TNBC in particular." (PMID 40818975, 2025).
glioblastoma (5 papers, 2015 to 2024). The most malignant astrocytic tumor (WHO grade IV). "Inhibition of either plexin-B2 or ANG was found to inhibit glioblastoma cell proliferation, invasion, and tumor growth in animal models." (PMID 37627074, 2023). "Resonating with our current study, we have also recently demonstrated that Plexin-B2 provides the biomechanical dynamics required for invasive growth of glioblastoma cells." (PMID 34650052, 2021). "In intracranial glioblastoma transplants, Plexin-B2 knockdown hindered invasive growth and perivascular spreading, and resulted in decreased tumor vascularity." (PMID 25762646, 2015). "Activation of Plexin-B2 by Sema4C ligand in glioblastoma cells induced actin-based cytoskeletal dynamics and invasive migration in vitro." (PMID 25762646, 2015). "Plexin-B2 also transduces sema4C signals in glioblastoma cells." (PMID 37627074, 2023). "Plexin-B2 was also found to promote glioblastoma progression induced by ANG/plexin-B2." (PMID 37627074, 2023). "In the TCGA glioblastoma samples, PLXNB2 expression was on average upregulated by more than 2.5-fold in classical and mesenchymal subtypes, and more than 1.5-fold in proneural and neural subtypes, while the expression levels of PLXNB1 and -B3 were largely similar between subtypes." (PMID 25762646, 2015). "Targeting the Plexin-B2 pathway may represent a novel therapeutic approach to curtail invasive growth of glioblastoma." (PMID 25762646, 2015). "Activation of plexin-B2 with sema4C also acts synergistically with HGF-activated MET to promote MET phosphorylation and to promote the progression of glioblastoma." (PMID 37627074, 2023). "In addition, we also analyzed survival probabilities of the four TCGA molecular subtypes of glioblastoma in relation to Plexin-B2 upregulation, which revealed no statistically significant survival differences when standard parameters were applied (>2-fold as threshold for upregulation)." (PMID 25762646, 2015).
prostate carcinoma (4 papers, 2020 to 2023). A carcinoma that arises from epithelial cells of the prostate gland. "In prostate cancer, plexin-B2 plays a role together with angiogenin in the regulation of the stemness of prostate cancer stem cells (CSC)." (PMID 37627074, 2023). "PLXNB2 has also been shown to be upregulated in prostate cancer and be inversely correlated with patient survival." (PMID 31942000, 2020). "Monoclonal antibodies of angiogenin and plexin-B2 sensitize prostate cancer stem cells to chemotherapy, highlighting the targeting potential of this regulation." (PMID 31942000, 2020).
Intellectual disability (3 papers, 2024 to 2025). "These defects parallel neural tube closure phenotypes in Plxnb2 knockout mice and align with recent reports of rare pathogenic PLXNB2 variants in patients with intellectual disability, underscoring clinical relevance." (PMID 41000649, 2025). "In cerebral organoids, Plexin-B2 ablation triggered premature cell-cycle exit and differentiation, resulting in progenitor pool depletion and neuroepithelial disorganization, phenotypes echoing intellectual disability in patients with rare pathogenic PLXNB2 variants." (PMID 41000649, 2025).
malignant glioma (3 papers, 2015 to 2021). A grade III or grade IV glioma arising from the central nervous system. "We show that Plexin-B2 is upregulated in malignant gliomas on both transcript and protein levels." (PMID 25762646, 2015). "In addition, PLXNB2 could serve as a prognostic marker and drug target for malignant glioma." (PMID 34367233, 2021).
pancreatic cancer (3 papers, 2022 to 2025). "We identify plexin B2 as a critical host-derived regulator of liver colonization in colorectal and pancreatic cancer and melanoma syngeneic mouse models." (PMID 39048831, 2024). "This included elements of the Hedgehog signaling pathway (SHH, GAS1), semaphorin signaling (SEMA3A, PLXNA1, PLXNB2, PLXND1, PLXNA2, FARP1, FARP2) and also axon guidance pathways (ROBO1, SLIT1, SLIT3 and SLITRK2), all notable for their involvement in pancreatic cancer progression and metastasis." (PMID 36429078, 2022).
amyotrophic lateral sclerosis (2 papers, 2022 to 2024). Amyotrophic lateral sclerosis (ALS) is a neurodegenerative disease characterized by progressive muscular paralysis reflecting degeneration of motor neurons in the primary motor cortex, corticospinal tracts, brainstem and spinal cord. "The mouse Plxnb2 gene was reported to control cerebellar granule cells’ development, and the human PLXNB2 gene was suggested to be relevant to amyotrophic lateral sclerosis (ALS) pathogenesis." (PMID 36614124, 2022).
Anxiety (2 papers, 2021 to 2022). Intense feelings of nervousness, tension, or panic often arise in response to interpersonal stresses. "Inhibition of amygdaloid Plxnb2 by its functional blocking monoclonal antibody (mAb)-102 induced mice anxiety (p<0.05), amygdaloid enlargement (p<0.05), and microglial ramification (p<0.001) compared to saline." (PMID 36325348, 2022). "In contrast, both Sema4C−/− and PB2−/−, PB2-LOFRhoA mouse lines showed impairment of behaviors related to both auditory-cued fear memory and anxiety, suggesting a role for Sema4C acting via Plexin-B2 in inhibitory amygdaloid circuits." (PMID 31444474, 2021). "To further understand the role of Sema4C-Plexin-B2 signaling in the amygdala, we tested anxiety behavior using elevated plus maze (EPM) test, which is linked to amygdala function." (PMID 31444474, 2021). "To condense, our study raises an idea of amygdaloid microglial activation in contribution to stress and anxiety, which may be leveraged by PLXNB2, and reveals a novel cellular and molecular mechanism in schizophrenia with different stress trait." (PMID 36325348, 2022). "Importantly, blocking of Plxnb2 in the amygdala induced anxiety and amygdaloid enlargement in otherwise normal mice." (PMID 36325348, 2022). "Furthermore, Plxnb2-inhibition in the amygdala induced anxiety and microglial activation in mice." (PMID 36325348, 2022).
asthma (2 papers, 2021 to 2022). "Some newly detected EV-related proteins were linked to asthma pathology: ezrin, contantin-1 (CNTN1) and Plexin B2 (PLXNB2)." (PMID 36466836, 2022).
colitis (2 papers, 2014 to 2022). Inflammation of the colon. "Additionally, CD100-plexin B2 regulation of γδ T cell-mediated tissue repair is critical in the dextran sodium sulfate (DSS) mouse model of colitis." (PMID 35480230, 2022).
cyst (2 papers, 2025). A sac-like closed membranous structure that may be empty or contain fluid or amorphous material. "Loss of Plexin-B2 disrupted apical polarity of neuroepithelium and depleted the progenitor pool through premature cell-cycle exit, resulting in smaller organoids with cyst-like structures and lineage instability." (PMID 41000649, 2025).
leukaemia (2 papers, 2021 to 2024). "In our previous study analysing data from The Cancer Genome Atlas database, PLXNB2 was associated with poor prognosis for patients with AML, and was likely to be involved in the regulation of leukaemia cell infiltration." (PMID 33757550, 2021). "Indeed, several mRNAs associated with the development of leukaemia, including Dusp6, Klf4, and Plxnb2, were significantly elevated in ECs and resting leukaemia cells after chemotherapy." (PMID 38674015, 2024).
melanoma (2 papers, 2016 to 2024). A malignant, usually aggressive tumor composed of atypical, neoplastic melanocytes. "PLXNA1 and PLXNB2 were in a region of copy loss in 10% of the samples and PLXNA4 was in a region of copy gain in two of the three melanomas that produced metastasis, suggesting that human melanomas harbor alterations of Plexins, in particular PLXNA4 amplification, as previously reported." (PMID 27095580, 2016).
oligodendroglioma (2 papers, 2015 to 2020). A well-differentiated (WHO grade II), diffusely infiltrating neuroglial tumor, typically located in the cerebral hemispheres. "Oligodendroglioma patients with upregulated PLXNB2 also exhibited a shorter median survival than those with intermediate level (24.9 vs. 29.3 months)." (PMID 25762646, 2015).
alveolar rhabdomyosarcoma (1 paper, 2022). A rapidly growing malignant mesenchymal neoplasm. "Our results indicate that Plexin-B2 can regulate cell migration in a selected cellular model of alveolar rhabdomyosarcoma." (PMID 35570846, 2022).
autism (1 paper, 2020). Persistent deficits in social interaction and communication and interaction as well as a markedly restricted repertoire of activity and interest as well as repetitive patterns of behavior. "The deletion of PLXNB2 and other genes was reported in an individual with autism and speech impairment." (PMID 32722525, 2020). "In our sequenced cohort of 134 individuals with autism and regression, we identified two recurrent variants, GRIN2A c.28C > A (p.Leu10Met) and PLXNB2 c.742C > T (p.Arg248Cys)." (PMID 32722525, 2020).
basal cell carcinoma (1 paper, 2021). A carcinoma involving the basal cells. "In line with this, we observed that expression levels of Plexin-B1 and Plexin-B2 in primary human basal cell carcinoma cells were low, and that re-expression of Plexin-B2 was sufficient to suppress YAP activity." (PMID 33637728, 2021). "To investigate a potential role of Plexin-B1 and Plexin-B2 for basal cell carcinoma progression in humans, we next studied primary human basal cell carcinoma cells." (PMID 33637728, 2021). "To test for a functional role of B-plexins in the control of YAP activity in human primary basal cell carcinoma cells, we engineered cells to re-express Plexin-B2." (PMID 33637728, 2021). "Indeed, Plexin-B2-expressing primary human basal cell carcinoma cells displayed less nuclear YAP and lower mRNA expression levels of YAP target genes than GFP-expressing control cells." (PMID 33637728, 2021).
brain cancer (1 paper, 2025). A primary or metastatic malignant neoplasm affecting the brain. "PLXNB2 is known to regulate neuronal migration and synaptogenesis and has previously been implicated in regulating cellular biomechanics, stemness, host microenvironment, and angiogenesis in brain cancer and other cancers." (PMID 40818975, 2025).
breast tumors (1 paper, 2025). "Breast tumor cells presented PLXNB2 in full-length ( ~ 200 kD) and truncated ( ~ 75 kD) proteins, both of which were lost upon CRISPR/Cas9 mediated gene knockout (KO)." (PMID 40818975, 2025). "For instance, other known ligands of PLXNB2, such as SEMA5A and SEMA4D, are either not expressed or not detectable in breast tumors at the primary site." (PMID 40818975, 2025).
experimental autoimmune encephalomyelitis (1 paper, 2022). An autoimmune demyelinating disease of the central nervous system that is produced experimentally in animals by the injection of homogenized brain or spinal cord in Freund's adjuvant. "In the CNS, PLXNB2 released by astrocytes caused inflammation in multiple sclerosis and experimental autoimmune encephalomyelitis by connecting with CD100 (the ligand of PLXNB2) in microglia." (PMID 35406030, 2022).
liver cancer (1 paper, 2022). An epithelial or non-epithelial malignant neoplasm that arises from the liver. "We detected multiple genomic HBV integrations in two distinct types of liver cancer, with recurrent events at TERT, ZMAT4, MET, ANKFN1, PLXNB2 in ICC, and TERT, ALKBH5 in CHC." (PMID 36123506, 2022).
mouth ulcers (1 paper, 2023). "Ultimately, we identified 6 potential risk genes (BTN3A3, IL12B, BPI, FAM213A, PLXNB2, and IL22RA2) of mouth ulcers with altered protein abundances in the blood." (PMID 37369724, 2023). "Second, by using Bayesian colocalization, two correlated signals with common causal variants can be estimated at specific sites, and the causative proteins of oral ulcers (BTN3A3, IL12B, BPI, FAM213A, PLXNB2, and IL22RA2) were validated." (PMID 37369724, 2023). "In conclusion, we found strong evidence supporting six novel blood proteins (BTN3A3, IL12B, BPI, FAM213A, PLXNB2, and IL22RA2) associated with mouth ulcers." (PMID 37369724, 2023). "However, only six genes (BTN3A3, IL12B, BPI, FAM213A, PLXNB2, and IL22RA2) assembled the criterion (PPH4 > 75%) in the analysis of mouth ulcers, indicating a shared single variant with mouth ulcers." (PMID 37369724, 2023). "Following this analysis, the researchers identified 6 key genes, namely BTN3A3, IL12B, BPI, FAM213A, PLXNB2, and IL22RA2, which were related to the onset of mouth ulcers." (PMID 37369724, 2023).
psoriasis vulgaris (1 paper, 2024). Plaque psoriasis is the most common presentation of psoriasis. "This may indicate a role of plexin-b2 in psoriasis vulgaris pathogenesis." (PMID 38734848, 2024).
rhabdomyosarcoma (1 paper, 2022). A rare aggressive malignant mesenchymal neoplasm arising from skeletal muscle. "Furthermore, we worked carefully to understand the isoforms of Plexin-B2 and the functional significance of Semaphorin ligands that bind to Plexin-B2 using small interfering RNAs of Plexin-B2 in rhabdomyosarcoma cell lines as a genetic proof of concept." (PMID 35570846, 2022).
schizophrenia (1 paper, 2022). A major psychotic disorder characterized by abnormalities in the perception or expression of reality. "Here, when investigating immune mechanisms underlying stress susceptibility in schizophrenia, we discovered the role of Plxnb2 in stress response." (PMID 36325348, 2022). "This preclinical evidence also corroborates a protective role of Plxnb2 in stress regulation, as aberrant fear behavior is a core stress-related symptom in many psychiatric disorders including schizophrenia." (PMID 36325348, 2022). "Since what we used here were adult mouse models with relatively acute effects, such as in the case of CUS and mAb microinjection, it doesn’t reveal schizophrenia-related neurodevelopmental changes in which Plxnb2 might be involved." (PMID 36325348, 2022). "In this sense, although we did not observe overt changes in number and morphology of astrocytes by mAb102, we did find reduced GFAP+astrocytes and therefore the potential contribution of astrocytic Plxnb2 to schizophrenia and stress disorders is worth pursuing more carefully in the future." (PMID 36325348, 2022). "PLXNB2 may hence contribute to schizophrenia pathophysiology already at the developmental stage." (PMID 36325348, 2022).
skin cancer (1 paper, 2021). "In summary, these data indicate that Plexin-B1/Plexin-B2 limit YAP activity and proliferative capacity not only during embryonic development but also in skin cancer in mice." (PMID 33637728, 2021).